AGR2 (anterior gradient 2, protein disulphide isomerase family member)
Diseases named in the same sentence as AGR2 in open-access papers (continued):
Sharing a sentence is not in itself a finding about the gene and the disease.
cancer (continued). "To investigate the effect of TGF-β treatment on AGR2 expression, we used four different cancer cell lines expressing various levels of EMT markers in order to generalize the role of AGR2 in response to TGF-β treatment." (PMID 28810836, 2017). "AGR2 expression and inflammation can thus be induced in pancreatic cells by transmission of ER stress from both cancer and stromal cells." (PMID 27941872, 2017). "Our findings demonstrate that AGR2 induced in ER-stressed and inflammatory pre-neoplastic pancreas is a potential marker of cancer progenitor cells with an important functional role in PDAC initiation." (PMID 27941872, 2017). "After PSA normalization, a significant difference between the cancer and non-cancer urine was observed for the marker peptides [except for LPQTLSR of AGR2, VTSLTACLVDQSLR of CD90 and MVIITTK of CXL14] with P = 0.015-0.035." (PMID 29254211, 2017). "In relation to molecular changes associated with EMT and MET phenotypes, AGR2 appears to be a key regulator of these processes indicating a dual role of AGR2 in cancer." (PMID 28810836, 2017). "The expression of cathepsins B and D is post-transcriptionally induced by AGR2 to promote cancer cell dissemination." (PMID 28402938, 2017). "Four AGR2-positive cancer cell lines showing different epithelial mesenchymal transition traits were selected to investigate the effect of TGF-β on EMT induction with respect to AGR2 expression." (PMID 28810836, 2017). "Prostate stromal cells were cultured, and tissue digestion media containing AGR2 prepared from prostate primary cancer 10-076 CP and adenocarcinoma LuCaP 70CR xenograft were added." (PMID 27283903, 2016). "We then employed 1 to develop a detection assay for AGR2, a potential cancer biomarker, as a “proof-of-principle” demonstration of the application of a linked complex for DNA-based detection in diluted fetal bovine serum." (PMID 28660021, 2016). "To further characterize the role of AGR2 in cancer, we assessed the impact of AGR2 depletion using the 3D human bronchial organoids system which we previously established." (PMID 27240165, 2016). "More significantly, cancer cells secrete AGR2 and the protein is found on the cell surface, whereas normal AGR2+ cells do not have expression on the cell surface as the protein is not secreted and is localized to the cell interior." (PMID 27283903, 2016). "In clinical utility, AGR2+ cancer cells can be targeted for eradication by agents such as antibodies or antibody drug conjugates, while AGR2+ normal cells would be spared." (PMID 26894971, 2016). "In this work, we investigated the effect of cancer-secreted AGR2 on normal prostate stromal cells in culture." (PMID 27283903, 2016). "Cancer-secreted AGR2 induces cell death in normal (prostate stromal) cells with down-regulation of SAT1, which is involved in polyamine metabolism." (PMID 27283903, 2016). "Taken together, these results show that overexpression of AGR2 in cancer cells increases their tumorigenic and metastatic potential." (PMID 27240165, 2016). "Further experiments then revealed that AGR2 also makes cells more invasive and capable of moving, both important features of aggressive cancer cells." (PMID 27240165, 2016). "We then employed 1 to develop a G-quadruplex-based sensing system for the detection of AGR2, a potential serum biomarker for cancer, as a “proof-of-principle” concept." (PMID 28660021, 2016). "Previous research has shown that AGR2 inside cancer cells can help them grow and survive and AGR2 can also be found outside cells, such as in the blood or the urine of cancer patients." (PMID 27240165, 2016). "Studies in the last decade demonstrated that despite the integrity of its KTEL signal (ER retention motif), the ER-resident AGR2 is secreted in various cancers." (PMID 27240165, 2016).
cancer (continued). "The cancer-specific secretion of AGR2 indicates an important functional role in cell-cell communication." (PMID 27283903, 2016). "In gastric cancer cells, AGR2 expression was found up-regulated in a cancer cell subline with high metastatic potential for invasion to lymph nodes." (PMID 26445321, 2015). "In these cancers, higher expression levels of AGR2 generally correlate with decreased patient survival time." (PMID 26169982, 2015). "Anterior gradient 2 (AGR2) is a protein disulfide isomerase-like protein widely expressed in many normal tissues as well as cancers." (PMID 26445321, 2015). "For this reason, overexpression of AGR2 is often reported in a number of cancers, particularly in those arising from the breast, prostate, ovary and pancreas." (PMID 26169982, 2015). "Extensive studies have demonstrated that cancer stem cells are abundant in chemotherapy and radiotherapy, which prompted our study on the correlation of AGR2 with self-renewal and pro-survival factors." (PMID 25871396, 2015). "AGR2 is overexpressed in multiple cancers, particularly those arising from breast and prostate tissues, and higher levels of AGR2 are associated with earlier patient death." (PMID 26169982, 2015). "A possible explanation is that AGR2 functions differently in the cancer cell types, or that other differentially expressed genes affect AGR2 function." (PMID 26445321, 2015). "AGR2 expression being a feature of low grade cancer appears to contradict the metastasis promoting property of AGR2." (PMID 26445321, 2015). "AGR2 expression in cancer cells induces the expression of amphiregulin (AREG) and in intestinal IEC-6 cells the transcription factor CDX2." (PMID 25111734, 2014). "Recently, much interest has focused on AGR2 for its potential roles in the invasion and metastasis of malignant tumors." (PMID 24717913, 2014). "AGR2 is a protein disulfide isomerase that is over-expressed in several human carcinomas and stimulates cancer cell proliferation, survival, invasion, and metastasis." (PMID 24976026, 2014). "Over-expression or suppression of AGR2, in different cancer model systems, affects cell proliferation, invasion, survival and metastasis." (PMID 24976026, 2014). "Drug resistance of cancer cells against gemcitabine and tamoxifen is also affected by AGR2 expression." (PMID 25367337, 2014). "SYCN, REG1B and AGR2 were also significantly elevated in PDAC compared to benign controls (p ≤ 0.01), and AGR2 was significantly elevated in PDAC compared to other cancers (p < 0.01)." (PMID 24007603, 2013). "The aptamer sequences and AGR2-aMB reported in this study are potentially useful tools for early diagnosis and prognosis of cancer and for fundamental research to elucidate the biochemical functions of AGR2." (PMID 23029506, 2012). "An AGR2 signal would then prompt nCounter testing to score the expression of other cancer markers for confirmation." (PMID 23029164, 2012). "This aptamer probe has great potential to serve as a useful tool for early diagnosis and prognosis of cancer and for fundamental research to elucidate the biochemical functions of AGR2." (PMID 23029506, 2012). "Activated AGR2 expression was identified in different human cancer cells and human AGR2 was shown to promote cell growth, so we performed p-Histone H3 immunostaining to investigate the role of agr2 in zebrafish intestinal cell proliferation." (PMID 22514630, 2012). "Activated AGR2 expression was found in different human cancer cells including breast, prostate, ovarian, esophagus, gastro-intestinal tract and lung, indicating a role in promoting cell proliferation." (PMID 22514630, 2012). "AGR2 has since been demonstrated to be estrogen and androgen responsive, and its upregulation has been reported in a number of cancers, including breast, lung, ovarian, gastric, pancreatic, esophageal, and prostate cancer." (PMID 20525379, 2010).
cancer (continued). "The array signal level for AGR2 in the cancer cells was ~50-fold higher than that in luminal cells, the normal counterpart." (PMID 21144054, 2010). "Initially, we asked how AGR2 knockdown would affect the effect of antiestrogens on cancer cell lines." (PMID 20525379, 2010). "Collectively, the data presented support the utility of anti-AGR2 therapy in ER-positive breast cancers because of its impact on cancer-relevant pathways." (PMID 20525379, 2010). "This impact on growth was seen with multiple AGR2 siRNA sequences, which supports the specificity of the effect of AGR2 knockdown on the inhibition of cancer cell growth." (PMID 20525379, 2010). "Several cancers, including breast, prostate, fibrolamellar, pancreatic, and colon, have been found to express increased levels of AGR2 compared to normal tissue." (PMID 21144054, 2010). "AGR2 was also readily detectable in the tissue digestion media of cancer specimens by Western blot analysis." (PMID 20021671, 2009). "A ~19-kDa AGR2 protein was detected in cancer tissue preparation by mass spectrometry of 2-D gel electrophoresis spot." (PMID 20021671, 2009). "The relative abundance of AGR2 mRNA correlated significantly with the class score for immunocytochemically detectable AGR2 protein in the cancer cells (Spearman's rank correlation statistic 0.36; P=0.0007)." (PMID 16598187, 2006). "Within the ERα-negative group, there was a positive correlation between the degree of staining for AGR2 (>1% carcinoma cells stained) and the degree of staining for PgR (n=47 cases; Spearman's correlation coefficient 0.48; P=0.0007)." (PMID 16598187, 2006). "For these analyses, the borderline staining group was combined with the positive staining group for AGR2, that is, using a 1% cutoff of the carcinoma cells staining." (PMID 16598187, 2006). "As AGR2 was identified as an oncogene in cancers, we hypothesized that AGR2 might be a negative regulator of ferroptosis." (PMID 41326375, 2025). "Interestingly, the strongest predictor of cancer cell dependence on AGR2 in the DepMap is the high expression of IRE1β (depmap.org), a paralog of IRE1α that is selectively expressed in mucus-producing cells of the lungs and intestines." (PMID 40867591, 2025). "Whether higher H6PD activity due to increased AGR2 expression promotes a more aggressive cancer cell phenotype, for example by altering energy metabolism, Ca2+-related processes or UPR and chaperone activation pathways, warrants further investigations." (PMID 40281598, 2025). "Furthermore, Agr2 can be secreted into the extracellular environment and has been detected in human urine and serum, highlighting its potential use as a cancer biomarker." (PMID 40471515, 2025). "Based on previous studies, Fibro_FAP was classified as inflammatory cancer-associated fibroblast (iCAF)-like, Fibro_ACTA2 as myofibroblastic cancer-associated fibroblast (myCAF)-like, and Fibro_HLA-DRA and Fibro_AGR2 as antigen-presenting cancer-associated fibroblast (apCAF)-like." (PMID 39722065, 2025). "AGR2 has been shown to promote cancer cell proliferation, invasion, and resistance to chemotherapy, and it may play a crucial role in regulating the ER’s ability to adapt to physiologic stress." (PMID 40459063, 2025). "Selectively targeting AGR2 expression in cancer may provide survival advantages for patients with tumors." (PMID 39062458, 2024). "Moreover, our findings reinforce the suitability of CMT as a complementary model for investigating AGR2 function in human cancer." (PMID 38822246, 2024). "Despite disparities in findings related to the effects of reducing AGR2, the multifaceted nature of cancer suggests that AGR2 may play varying roles at different expression levels, potentially influencing the entirety of cancer development." (PMID 39062458, 2024).
cancer (continued). "While the exact mechanism of this regulation is still unclear, one potential target could be AGR2, which was the most downregulated protein in EPCART-del cells according to proteomics results and has been associated with mTORC2 in cancer." (PMID 39147845, 2024). "The elevated AGR2 expression was indicative of cancer cell differentiation induced by PENK." (PMID 38595814, 2024). "Moreover, upregulation of AGR2 expression is seen in chemotherapeutics-resistant cancer cells, further contributing to drug resistance." (PMID 38822246, 2024). "Though the utility of urine AGR2 as a cancer marker may require further validation with larger sample sizes and stable sample collection methods, it presents a promising avenue for non-invasive, cost-effective diagnostic tests." (PMID 39062458, 2024). "Notably, AGR2 not only serves as a pro-oncogenic agent but also as a downstream targeting protein, indirectly fostering cancer progression." (PMID 39062458, 2024). "Moreover, AGR2 can be leveraged as a monoclonal antibody, such as 18A4, to enhance the efficacy of other cancer treatments, significantly augmenting the inhibitory impact of drugs on cancer cells." (PMID 39062458, 2024). "Additional studies may be warranted to explore the targetability of cell surface AGR2, although our data cast doubt on its utility as a target for anti-cancer T-cell therapy." (PMID 39727484, 2024). "In summary, AGR2 holds a central role in cancer progression and immunotherapy." (PMID 39062458, 2024). "Our study and those of others show a prominent role of AGR2, and extracellular AGR2 in particular, in cancer cell migration, although if and how this motility function is important for normal colon cells is unknown." (PMID 39727484, 2024). "Perhaps not coincidentally, AGR2 has been reported to be secreted from cancer cells and found to be associated with the cell surface." (PMID 39727484, 2024). "Given this evidence, it can be inferred that decreased AGR2 levels compromising mucosal layer integrity may play a significant role in cancer invasion." (PMID 39062458, 2024). "Moreover, the correlation of AGR2 function with cancers such as hepatobiliary and pancreatic malignancies offers valuable insights for cancer treatment." (PMID 39062458, 2024). "Addressing secreted 14-3-3ε and α-actinin 4 in addition to AGR2 in the microenvironment could offer novel insights into cancer treatment strategies." (PMID 38822246, 2024). "AGR2 is ubiquitously present in a wide array of cancer types, and investigating its distribution mechanism could potentially enhance cancer detection and treatment strategies." (PMID 39062458, 2024). "Collectively, our preliminary data highlight a novel regulatory mechanism of AGR2 that may serve as a critical determinant of cancer progression and drug resistance in HCC." (PMID 36899352, 2023). "The current results together with the published work reveal an intricate regulatory network between TGF‐β signaling and ESE1/AGR2 axis that function together with other EMT drivers such ZEBs to govern the normal epithelial homeostasis or EMT phenotype in cancer cells." (PMID 36329620, 2023). "In addition, the KTEL motif in AGR2 also plays a functional role in the metastasis pathway of cancer cells." (PMID 37197416, 2023). "With the gradual deepening of research, the key regulation of AGR2 in cancer is gradually clear." (PMID 37197416, 2023). "Using these AGR2 mutants, we will be able to determine whether the subcellular location of AGR2 plays a critical role in regulating cancer progression and sorafenib resistance." (PMID 36899352, 2023). "Intracellular AGR2 is a catalyst for the protein balance of endoplasmic reticulum to meet the secretory needs of cancer cells, while extracellular AGR2 is involved in the pro cancer signal transduction of epithelial tumorigenesis, ECM remodeling, inflammatory response and angiogenesis." (PMID 37197416, 2023).
cancer (continued). "In conclusion, we emphasize that AGR2 can be found in the body fluid of cancer patients, and its expression level can be distinguished from that of normal patients, which means that AGR2 may be used as a cancer marker for diagnosis or prognosis." (PMID 37197416, 2023). "AGR2 was shown to be present in the extracellular space, serum, and urine of patients with cancer." (PMID 37175601, 2023). "If we can find a protein corresponding to the AGR2 specific peptide motif, which can compete with the client protein in the carcinogenic pathway to bind AGR2, it will help to weaken the role of AGR2 in cancer growth and metastasis." (PMID 37197416, 2023). "In addition, this secreted AGR2 can be found in the body fluid of cancer patients, and the expression level can be distinguished from normal patients, which indicates that AGR2 can be used as a marker for diagnosis, prognosis and drug resistance." (PMID 37197416, 2023). "Therefore, clarifying the upstream and downstream proteins involved in AGR2 interactions and regulating the activity of AGR2 proteins by intervening in related molecular pathways is a strategy for inhibiting cancer growth and metastasis." (PMID 37197416, 2023). "The secretion of extracellular AGR2 in cancer may be due to the saturation of endoplasmic reticulum receptor sites, because AGR2 is overexpressed in cancer cells." (PMID 37197416, 2023). "Therefore, we used reversible crosslinking followed by pull down (PD) of AGR2 complexes and high-resolution LC–MS/MS to identify proteins interacting with AGR2 in order to assign the role of found complexes to respective signaling pathways in cancer cells." (PMID 34929376, 2022). "The question underlying the development of this work is whether AGR2 and AGR3 can be considered as playing a major role in oncogenesis and progression of cancers; in other terms, whether they can be considered as oncogenes and/or TSG." (PMID 35857928, 2022). "It has been suggested that AGR2 plays dual roles in cancer development." (PMID 35965326, 2022). "AGR2 is also involved in the development and progression of multiple tumors, including pancreatic, prostate, colorectal, breast, and endometrial cancers." (PMID 36003068, 2022). "AGR2 was the other biomarker that appeared upregulated in most cancers." (PMID 36428623, 2022). "In parallel, the role of PGE2 in regulating the inflammatory milieu that drives cancer onset and progression could also be connected with induced AGR2 expression in malignant cells." (PMID 36142758, 2022). "Several lines of evidence indicate that TGF-β attenuates AGR2 expression in human cancer cells." (PMID 36142758, 2022). "Heatmap analysis of the top differentially expressed genes (DEGs) delineated the signatures of each cell type among the six positive lymph nodes, with cancer cells highly expressing genes includingTFF1,AGR2,TFF3, and myeloid cells highly expressing genes includingC1QB,RNASE1 andAPOE." (PMID 36148946, 2022). "Interestingly, literature search for the last 10 years revealed that PDIA3 (also ERp57 or GRP58) along with AGR2 had attracted the most attention in relation to cancer research." (PMID 34929376, 2022). "Additionally, AGR2 stabilizes hypoxia inducible factor-1α, indicating a role of this chaperone in the chemoresistance of cancer cells." (PMID 33717413, 2021). "Notably, AGR2 can be found in the extracellular matrix of cultured cells and the serum or urine of cancer patients." (PMID 33413231, 2021). "Furthermore, AGR2 activates the mammalian target of rapamycin complex 2 (mTORC2) pathway and promotes cancer metastasis." (PMID 34632938, 2021). "AGR2 has since been shown to be an endoplasmic reticulum (ER) localized protein disulfide isomerase superfamily member that is upregulated in a large number of human cancers." (PMID 34200338, 2021).